IL33 (interleukin 33)
Diseases named in the same sentence as IL33 in open-access papers (continued):
Sharing a sentence is not in itself a finding about the gene and the disease.
colitis (continued). "As IL-33 may be protective in human IBD, expanded studies correlating Sprouty2, IL-33, and colitis outcomes will be important to pursue to determine whether SPRY2 acts as a biomarker for disease severity." (PMID 33547321, 2021). "Interestingly, CD90+CD74+ inflammatory fibroblasts express IL-33 and are increased in DSS-induced colitis, indicating this population is likely responsible for the increases in Il33 in acute colitis induced by epithelial damage." (PMID 33953267, 2021). "IL-33 is known to be constitutively expressed at high levels in the nucleus of epithelial cells and its expression is further elevated in active lesions of IBD patients and mice with DSS-induced colitis." (PMID 34335571, 2021). "Breg-like cells (IL-33 + Breg) isolated from mice with IBD inhibited the expansion and functioning of immune effector cells and effectively prevented the development of spontaneous colitis in IL-10 − / − mice after adoptive metastasis." (PMID 33462754, 2021). "The lack of increased Il33 expression Il10−/− mice with colitis stands in stark contrast to the increased Il33 expression consistently observed in human UC7–10,17." (PMID 33953267, 2021). "Stable colonization of mice with the Crohn’s disease-associated pathobiont adherent invasive E. coli, permitted only after colitis induced by Salmonella or DSS, also results in marked upregulation of IL-33 and the IL-33 receptor, which contributes to intestinal fibrosis in this model." (PMID 33953267, 2021). "IL-1β induces Il33 in colon myofibroblasts in vitro, but signaling through the IL-1R1 is not necessary for induction of IL-33 in DSS-induced colitis." (PMID 33953267, 2021). "In an experiment whereby the N-terminus of IL-33 was altered such that it could not associate with chromatin, the result was the formation of a whole-body inflammatory response with splenomegaly, increased lymph node infiltration and indeed development of colitis." (PMID 31139196, 2019). "Mice lacking IL-33 had worse DSS-induced colitis than WT mice, but this effect was reversed by cohousing the IL-33−/− mice with WT mice." (PMID 31455422, 2019). "Conversely, IL-33's effects in a Th1-driven model, such as in TNBS colitis or DSS-induced chronic colitis, may result in decreased intestinal inflammation mediated by cytokine and cell-mediated modulation of immune responses." (PMID 30539029, 2018). "The authors reported that intestinal epithelial proliferation and apoptosis were unaffected by the absence of IL-33 or ST2 in this model of colitis, but that goblet cell numbers and Muc2 expression were decreased in these mice." (PMID 29922293, 2018). "The mrIL-33-treated mice exhibited slightly longer life spans than the TNBS-treated mice, although this trend was not statistically significant, suggesting that IL-33 exerts protective effects against Th1-mediated colitis." (PMID 28404987, 2017). "IL-33 was shown to increase both ST2 and Foxp3 levels and expand Tregs in mice with colitis." (PMID 28484466, 2017). "We found that IL-33 induced M2 macrophages in both mouse models of colitis and human MDMs, even though IL-33 did not significantly affect Th2 or Treg populations in the mouse models." (PMID 28404987, 2017). "Our data suggest that IL-33 ameliorates colitis through its effects on innate immunity rather than adaptive immunity." (PMID 28404987, 2017). "Adoptive transfer of these IL-33-treated, IL-10-producing B cells prevented spontaneous colitis in IL-10−/− mice without affecting Treg frequency." (PMID 28484466, 2017). "All in all, IL-33 plays a complicated role in SAMP1/YitFc (SAMP) mice, DSS-induced colitis, oxazolone (OXA) colitis and TNBS-induced experimental colitis, which might be a result from discrepancy of dominated immune response." (PMID 28423665, 2017). "However, in another model of colitis, which is induced by trinitrobenzene sulfonic acid (TNBS), the protective role of IL-33 was also observed." (PMID 26082774, 2015).
colitis (continued). "Expression of IL-33 and its ST2 receptor was consistently up-regulated in the intestinal mucosa of patients with UC and to a lesser extent in CD patients, as well as animals with colitis." (PMID 25937893, 2014). "In an earlier study, Imaeda and colleagues showed that while peritoneal injection of IL-33 could accelerate the disease, the treatment also prevented the depletion of goblet cells in the DSS-induced colitis, possibly through inhibition of the Notch signalling." (PMID 24491821, 2014). "In fact, IL-33 appears to enhance intestinal inflammation in disease models, which are driven by Th2 and innate immune responses, such that observed in SAMP mice and the acute phase of DSS colitis, and possibly in UC patients." (PMID 23766561, 2013). "Using this model, mice developed less severe colitis following intraperitoneal injections of IL-33, whereas anti-IL-33 antibody administration did not significantly affect intestinal inflammation." (PMID 23766561, 2013). "Conversely, IL-33's effects during a Th1-driven model, such as in TNBS colitis, may result in decreased intestinal inflammation mediated by cytokine and cell-mediated modulation of immune responses." (PMID 23766561, 2013). "In a T-cell-driven adoptive transfer (AdTr) colitis mouse model, liraglutide significantly improved disease activity markers, including histological activity in colonic tissue and the colon weight-to-length ratio, likely due to its ability to reduce CCL20, IL-33, and IL-22." (PMID 40426955, 2025). "Dietary inulin elevated microbiota-derived bile acids, which induced IL-33 expression and promoted the expansion of inflammatory ILC2s that preferentially secrete IL-5 but not AREG, leading to eosinophil accumulation and exacerbation of DSS-induced colitis in mice." (PMID 40498001, 2025). "Regardless of the debate, utilizing a TNBS-induced colitis mouse model (BALB/c) demonstrated that IL-33 may accelerate the transition from Th1 to Th2 response, ultimately relieving Th1-type inflammation." (PMID 37686309, 2023). "However, the administration of recombinant IL-33 for enhancement of Treg-mediated protective function may be time-dependent, as IL-33 administration at initiation of DSS-induced colitis worsened disease severity." (PMID 36614065, 2022). "We found that Il33 is significantly increased in DSS-induced colitis, but not in Il10−/− colitis." (PMID 33953267, 2021). "Interestingly, IL-33 is strongly induced during DSS-induced colitis, but not during IL-10–/– chronic colitis." (PMID 33953267, 2021). "Indeed, adoptive transfer of peritoneal macrophages with or without IL33, which can induce the proliferation and alternative activation of peritoneal macrophages, ameliorated inflammation in a preclinical colitis model." (PMID 34911964, 2021). "Our previous studies showed that IL-33 was markedly increased in the mice with TNBS-induced colitis, while rIL-33 treatment had a significant beneficial effect on Th1/Th17-mediated experimental colitis through promoting alternatively activated macrophage polarization and Tregs differentiation." (PMID 30863362, 2019). "Similarly, IL-33 signaling on TREG cells was shown to play an important role in enhancing the stability of Foxp3 in TREG cells and is notably necessary for these cells to prevent T cell-mediated colitis." (PMID 30949175, 2019). "On the one hand, mucosal IL-33 levels correlated with disease severity in IBD patients and in mice with experimental colitis, and lack of IL-33 or ST2 attenuated dextran sodium sulfate-induced colitis by protection against IL-33-mediated epithelial damage and enhanced wound healing response." (PMID 30213101, 2018). "Taken together, our results indicate that goblet cell modulation by IL-33 might be directly influenced by IL-33 itself or by other non-T cells, such as macrophages, but independently of the MyD88 pathway during colitis." (PMID 28404987, 2017).
colitis (continued). "Indeed, in some models of colitis the absence of the IL-33/ST-2 axis is protective, suggesting a pathologic role of IL-33; while in others the absence of IL-33 results in reduced recovery and mouse death, indicating a protective role." (PMID 24520333, 2014). "Moreover, Gurtner’s experiments using a DSS-induced colitis model demonstrated that IL-33 and IFN-γ synergistically promote an increase in the A-Eos subset (with antimicrobial and cytotoxic properties) in colonic eosinophils, hence minimizing colitis aggravation." (PMID 37686309, 2023). "However, studies have not examined the role of endogenous IL-33 in a chronic model of colitis." (PMID 33953267, 2021). "Therefore, tissue‐prevalent mast cells stimulated by a combination of IL‐3 and IL‐33 would secrete high levels of IL‐6, but not IL‐2, and represent potential mediators of the negative regulatory role of IL‐3 in colitis‐mediated immune responses by induction of RORγt+ Tregs." (PMID 33427298, 2021). "However, IL-33 in our study did not exacerbate the disease activity, but ameliorated the colitis." (PMID 28404987, 2017). "Consistently, adoptive transfer of ILC2s expanded in mice treated with IL-33 into mice with DSS-induced colitis, resulting in a significant improvement in the severity of colitis compared to mice without ILC2 transfer." (PMID 36268010, 2022). "In PTENΔDC mice, we found elevated IL-6 serum levels, but no changes in IL-33 or CXCL-1 (also known as KC), which previously have been shown to be increased during colitis." (PMID 35514976, 2022). "Colon Il33 was induced in WT and Il10−/− mice exposed to DSS, but not in unchallenged Il10−/− mice with colitis." (PMID 33953267, 2021). "Although IL-1β induced IL-33 expression in vitro, using Il1r1−/− mice, we showed this signaling pathway is not required for Il33 induction during DSS-induced colitis." (PMID 33953267, 2021). "Hence, small differences towards reduction of pro-inflammatory IFN-γ producing cells and increase of protective cytokines (IL-33) or enzymes (Cox-2) may be responsible for the overall protective effect of FM against colitis and may not reach statistical significance when considered individually." (PMID 24520333, 2014). "In patients with IBD, ILC2s were more frequently observed compared to their near absence in mucosal samples from non-IBD individuals, and IL-33 expression was correspondingly increased in the colonic tissue of both IBD patients and dextran sulfate sodium (DSS)-induced colitis." (PMID 40498001, 2025).
eosinophilia (132 papers, 2008 to 2026). "Relevant polymorphisms, such as those located in the IL33 promoter or enhancer, are associated with increased IL-33 production and eosinophilia." (PMID 41087719, 2025). "CRSwNP patients, particularly those resistant to treatment, were associated with increased levels of tissue and blood eosinophilia and concomitant IL-33 upregulation in nasal polyp tissues." (PMID 38137606, 2023). "This prospective study observed that serum levels of sST2 and IL-33 were increased in CRSwNP patients and were associated with mucosal eosinophilia and postoperative recurrence." (PMID 35633657, 2022). "T-helper 2 (Th2) associated responses, such as production of interleukin 33 (IL-33), (interleukin 13) IL-13, (interleukin 4) IL-4 cytokines, and eosinophilia, are generally considered to be detrimental." (PMID 29463005, 2018). "IL-33 is known to contribute to AHR since animal studies demonstrated that intranasally administered IL-33 results in an AHR-association with eosinophilia, goblet cell hyperplasia, and accumulation of IL-4, −5 and −13 in the lungs." (PMID 25849971, 2015). "Additionally, intranasal IL-33 challenge upregulated ILC2s in the esophagus, inducing hallmark EoE characteristics such as basal-cell proliferation, epithelial thickening, and eosinophilia." (PMID 39653767, 2025). "In NLF from infants hospitalized with RSV bronchiolitis, elevated IL33, among other Th2 cytokines and low levels of IFNγ, was detected in the acute phase of the disease, predisposing them to allergic inflammation and favoring eosinophilia." (PMID 36561744, 2022). "Here we show that Hp‐TGM could alleviate airway and lung tissue eosinophilia, in association with control of IL‐5 and IL‐33 cytokine levels at 24 h, or either IL‐4 and eotaxin‐1, or IL‐4 and IL‐13 responses in T‐cell mediated models." (PMID 35758054, 2022). "Finally, it has been shown that, in association with enhanced eosinophilia, IL-33 is also required for the appropriate accumulation of helminth-protective ILC2s." (PMID 32363166, 2020). "In accordance with these findings, we see IL-33 treatment increases IL-5 levels during C. difficile infection, and adoptive transfer of ILC2s causes increased eosinophilia in the colon during C. difficile infection in addition to preventing CDI-associated weight loss and mortality." (PMID 31221971, 2019). "Airway hypersensitivity reactions (AHRs) and eosinophilia are reduced in IL-33-deficient mice." (PMID 28819104, 2017). "Schmitz and co-workers demonstrated that injection of IL-33 into mice induced a profound eosinophilia with associated pathologic changes, and had potent effects on eosinophil, including the induced production of superoxide anion and IL-8, degranulation and eosinophil survival." (PMID 24507763, 2014). "Genetic deletion of the N‐terminal domain, resulting in uncontrolled IL‐33 release from cells, results in multi‐organ eosinophilia and death in mice." (PMID 40944312, 2025). "Localization in the nucleus is essential for regulating IL-33 release in the serum and subsequent type 2 immune responses, including eosinophilia, as well as systemic inflammation." (PMID 41087719, 2025). "Cholic acids precipitated stromal IL-33 release, subsequently activating ILC2s to secrete IL-5, thereby promoting tissue eosinophilia and inflammation." (PMID 41313018, 2025). "Itepekimab, an anti-IL-33 antibody, effectively engages its target and mitigates tissue eosinophilia, while CM310-stapokibart, tralokinumab, and lebrikizumab inhibit IL-4/IL-13 signaling with variable efficacy depending on patient biomarkers." (PMID 40732309, 2025). "Another contributor, miR-21-5p, upregulates IL-33 via the GLP-1R/IL-33 axis, promoting Th2-skewed inflammation and eosinophilia." (PMID 39996835, 2025). "Recently, deletion of A20 in macrophages was reported to suppress IL-33-dependent expansion of lung ILC2s, type-2 cytokine production, and eosinophilia." (PMID 38680500, 2024).
eosinophilia (continued). "The present study is one of the few that simultaneously analyze and correlate the levels of IL-33 from NP tissue in CRSwNP human subjects with blood eosinophilia and overall disease severity score." (PMID 38137606, 2023). "ILC2s produce large amounts of IL-5 and IL-13 in response to activation with IL-33, resulting in eosinophilia and this has been adopted as a robust model for innate induction of airway inflammation." (PMID 35711456, 2022). "Intranasal administration of Hp‐TGM during Alternaria exposure sharply reduced airway and lung tissue eosinophilia along with bronchoalveolar lavage fluid IL‐5 and lung IL‐33 cytokine levels at 24 h." (PMID 35758054, 2022). "Our findings confirm previously reported reduced airway eosinophilia after rapamycin treatment in IL-33-exposed mice." (PMID 35720347, 2022). "As expected, IL-33 induced airway and bone marrow eosinophilia and elevated CCL24/eotaxin-2 levels in BALF compared to control groups." (PMID 35720347, 2022). "Since IL-33 treatment upregulated colonic eosinophils, we asked if IL-33-mediated protection was dependent on eosinophilia." (PMID 34400793, 2022). "The effect of IL-33 is dependent on ILC2-driven lung eosinophilia, which restricts extracellular glucose availability and impairs the glycolysis-dependent effector functions of lung NK cells." (PMID 35979357, 2022). "A recent study demonstrated that inhibition of mAChR signaling with tiotropium attenuated ILC2 proliferation, type 2 cytokine production and eosinophilia in papain and IL-33-driven models of airway inflammation." (PMID 35711456, 2022). "Other studies on IL-33-induced airway hyperreactivity demonstrated a link between IL-33 and mucus overproduction, goblet cell hyperplasia, and eosinophilia, as well as elevated chemokines and cytokines in the lungs." (PMID 36311787, 2022). "Coordinately, flow-cytometric analysis of cecal tissue revealed that administration of IL-33 resulted in eosinophilia during amebic infections." (PMID 34400793, 2022). "Through treating Rag-/- mice with IL-33 and IL-2c, a significant reduction in IL-33-induced lung eosinophilia occurred with extensive generation of ILC210s." (PMID 36275689, 2022). "ROS scavengers can reduce the production of IL-5 and IL-13, ILC2 proliferation, and ILC2-mediated eosinophilia in response to IL-33 stimulation." (PMID 35979357, 2022). "IL-33 is an important driver of eosinophilia, promoting both eosinophil development and survival, and a chromosomal duplication encompassing the IL-33 gene was recently identified in a patient with hypereosinophilia and atopy." (PMID 36546480, 2022). "Early animal studies targeting IL-33 were encouraging, with a reduction in bronchoalveolar fluid eosinophilia and airway hyperresponsiveness to methacholine." (PMID 33917396, 2021). "These Tregs, in turn, suppress the development of papain- or IL-33-induced eosinophilia in the lung." (PMID 34868033, 2021). "Intratracheal exposure to S. aureus derived serine protease-like protein (Spl) D upregulated IL-33 production in the lung leading to eosinophilia, bronchial hyperreactivity, and goblet cell hyperplasia in the airways." (PMID 33445787, 2021). "IL-33 injections also induce eosinophilia and splenomegaly in lean and obese mice although the degree of eosinophilia was higher in lean mice." (PMID 34948083, 2021). "The most important findings revealed that the IL-33/ST2 pathway is involved in eosinophilia, hepatic and cerebral parasitic burden, and induces the formation of granulomas related to tissue damage and pulmonary dysfunction." (PMID 34324507, 2021). "IL-33 challenge led to BAL eosinophilia, increased BAL neutrophils, increased pulmonary ILC2s and thus augmented lung inflammation in isotype-treated cohort, when compared to CD200-Fc-treated mice." (PMID 33953190, 2021).